KCNE1 (potassium voltage-gated channel subfamily E regulatory subunit 1)
Diseases named in the same sentence as KCNE1 in open-access papers (continued):
Sharing a sentence is not in itself a finding about the gene and the disease.
Arrhythmia (continued). "Taken together, although several KCNQ/KCNE1 activators have been reported, there are some limitations, including the low efficacy and the lack of specificity, that have to be overcome when thinking about the clinical use of these activators for the treatment of LQTS and cardiac arrhythmias." (PMID 33322401, 2020). "MiR-1 is the most abundant microRNA in the adult mouse heart, accounting for 35–40% of the total amount of miRNA MiR-1 directly targets connexin-43, KcnJ2, Kcne1, Ncx1, PP2A/RyR2, and Hcn4 in the adult heart, contributing to the arrhythmias that we and others observed in miR-1 TG adult hearts." (PMID 30936836, 2019).
deafness (11 papers, 2009 to 2025). An inherited or acquired condition characterized by the complete loss of the ability to hear from one or both ears. "In mouse, mutations in genes expressed by marginal cells of the SV, including Slc12a2, Atp1b2, Kcnq1, and Kcne1, result in a loss or reduction of EP and deafness." (PMID 34566577, 2021). "Null mutations in either Kcne1 or Kcnq1 disrupt endolymph production and K+ circulation in the inner ear, causing deafness and vestibular dysfunction." (PMID 33514733, 2021). "Using deafness panel sequencing, we excluded KCNE1 gene mutation which was identified as the cause of JLNS and found a novel compound heterozygous mutation c.1741A>T/c.477+5G>A in KCNQ1 gene of proband 1-II-1." (PMID 32508908, 2020). "A prominent role of the KCNE1 subunit in auditory perception is underscored by degeneration of sensory hair cells and deafness in KCNE1 knock-out animals, plus deleterious effects of a spontaneous KCNE1 null mutation on hearing in mice." (PMID 24710009, 2010). "In addition, we identified potentially novel deafness-associated genes Mpzl2 in IMCs and Tbx1 in MCs along with the known deafness-associated genes in IMCs (Kcnj10, Met, Mitf, Gjb6, Ednrb, and Gjb2) and in MCs (Kcnq1, Esrrb, Kcne1, Lrp2, Slc22a4, and Hgf)." (PMID 37322474, 2023). "Mutations in KCNQ1/KCNE1 result in human deafness and have been reviewed previously." (PMID 34566577, 2021). "Furthermore, the two affected individuals (V:6,VI:3) homozygous for the variant identified in KCNE1 also had long QT intervals in addition to hearing loss, while the other two affected individuals (IV:5,VI:5) had epilepsy and deafness." (PMID 31835641, 2019). "In the future, this approach may be used to test the feasibility of treating other inherited deafness cases in which the SV is the predominant site affected (e.g. mutations in KCNE1, CCDC50, DFNA5, MYH14, TFCP2L3, TMPRSS3 genes)." (PMID 26084842, 2015). "All seven of these families have variants in seven different known deafness genes, LRTOMT, LHFPL5, TMPRSS3, OTOF, MYO15A, ESRRB, and KCNE1." (PMID 31835641, 2019). "MinK knock-out mice display inner ear defects with deafness similar to what is observed in patients with JLNS, again highlighting the relevance of the KCNQ1/KCNE1 channel complex in the inner ear." (PMID 33498651, 2021). "For instance, KCNE1- or KCNQ1-null mice show severe collapse of the scala media and deafness, implying that KCNQ1/KCNE1 K+ channels are crucial for driving K+ transport and maintaining the endolymph." (PMID 27568193, 2016).
hearing loss (9 papers, 2010 to 2026). "Candidate genes for the disorder include KCNE1, a potassium channel subunit gene that has been implicated in maturation defects of central vestibular neurons, in Menière's disease, and in noise-induced hearing loss." (PMID 24710009, 2010). "They found that three SNPs in KCNE1, one SNP in KCNQ1, and one SNP in KCNQ4 were significantly associated with noise-induced hearing loss." (PMID 33801540, 2021). "Two SNPs, the rs2070358 G allele in KCNE1 and rs34287852 G allele (c.1365T>G, p.H455Q) in KCNQ4, were reported to be significant in both populations, with the rs2070358 G allele increasing the susceptibility to noise-induced hearing loss." (PMID 33801540, 2021). "In the SV, mutated genes related to ion channels and their regulatory subunits (e.g., KCNE1, KCNQ1 and KCNJ10) may lead to hearing impairment." (PMID 40600354, 2026).
channelopathies (5 papers, 2010 to 2024). "In 2020, the ClinGen Channelopathy Working Group assessed KCNE1 as having only limited evidence for association with congenital type 5 long QT syndrome (LQT5) and strong evidence for association with acquired long QT syndrome." (PMID 38816749, 2024). "The channelopathies are associated with the following genes: SCN5A, KCNQ1, KCNH2, KCNE1, RYR2." (PMID 38793126, 2024). "Regarding the etiology of channelopathies such as the Congenital Long QT Syndromes itself, 75% of LQTS cases are linked to mutations in genes encoding for voltage-gated potassium channel subunits (KCNQ1, KCNH2, KCNE1, KCNE2), or for voltage-gated sodium channel SCN5A." (PMID 36421220, 2022). "When the autopsy does not show any structuralcardiac anomaly, channelopathies he following panel of genes: SCN5A, KCNQ1, KCNH2, KCNE1, and RYR2 should be used." (PMID 38793126, 2024).
epilepsy (5 papers, 2019 to 2026). A brain disorder characterized by episodes of abnormally increased neuronal discharge resulting in transient episodes of sensory or motor neurological dysfunction, or psychic dysfunction. "In a prospective study the p.D85N SNV mutation in the KCNE1 gene was described in a patient with epilepsy and LQTS." (PMID 41062843, 2026). "Both KCNQ1 and KCNE1 are reported to be expressed in the brain, where KCNQ1 interacts with KCNE1, and there have been several reports that KCNQ1 variants are associated with both LQTS and epilepsy." (PMID 39100276, 2024). "Indeed, mutations of KCNQ1, KCNE1, and SCN5A could also be found in certain epilepsy patients." (PMID 32848785, 2020).
cardiomyopathy (4 papers, 2017 to 2025). A disease of the heart muscle or myocardium proper. "In particular, the KCNE1, MYBPC3, and AKAP9 genes that were associated with LQTS or cardiomyopathy would have been suspicious as genes associated with cause of death because of an AD mode of inheritance." (PMID 34728707, 2021).
long QT syndrome 5 (4 papers, 2014 to 2024). Any long QT syndrome in which the cause of the disease is a mutation in the KCNE1 gene. "Loss-of-function KCNE1 variants cause type 5 long QT syndrome (LQT5) via two major mechanisms: reduced cell surface expression and/or defective gating (activation of the IKs complex)." (PMID 38816749, 2024). "Additionally, loss-of-function mutations in KCNE1 have been associated with long QT-syndrome 5, which points out the important role of KCNE1 for the generation of IKs." (PMID 24600393, 2014). "Mutations in KCNE1, which encodes the β-subunit of the slow-activating delayed rectifier potassium channel (IKs) in cardiomyocytes, are associated with long QT syndrome 5 (LQT5)." (PMID 39272981, 2024).
torsades de pointes (4 papers, 2009 to 2025). A malignant form of polymorphic ventricular tachycardia that is characterized by heart rate between 200 and 250 beats per minute, and qrs complexes with changing amplitude and twisting of the points. "As Kv7.1 together with KCNE1 constitutes the molecular correlate of the slow repolarising current in the heart (the IKs current), this observation could indicate safety liability and potential for inducing torsades de pointes." (PMID 20011514, 2009).
heart failure (3 papers, 2015 to 2023). Inability of the heart to pump blood at an adequate rate to meet tissue metabolic requirements. "The influence of Kcne1 in heart failure was previously reported." (PMID 25646840, 2015).
Hypokalemia (3 papers, 2008 to 2020). An abnormally decreased potassium concentration in the blood. "The relevance of Kv7.1/KCNE1 channels for renal function is further underlined by the observation that KCNE1 knockout mice suffer from hypokalemia, urinary and fecal salt wasting, and volume depletion." (PMID 22876232, 2012). "Murine models have also been useful in studying the consequences of alterations in the potassium (K+) channel, such as mutations in the KCNE1 subunit resulting in LQT5 and of acute conditions such as hypokalaemia." (PMID 19351516, 2008). "That hypokalemia did not produce larger changes in ventricular repolarization is likely explained by the fact that repolarization of ventricular action potential in guinea pigs is more dependent on the IKs (KV7.1/KCNE1) current as compared to IKr (KV11.1)." (PMID 32508659, 2020).
Jervell and Lange-Nielsen syndrome (3 papers, 2014 to 2020). An autosomal recessive inherited syndrome caused by mutations in the KCNE1 and KCNQ1 genes. "Jervell and Lange-Nielsen syndrome is caused by homozygous or compound heterozygous mutations in KCNQ1 on 11p15.5 or KCNE1 on 1q22.1-q22.2." (PMID 28364778, 2017). "KCNE1 also regulates KCNQ1 in the inner ear, which is why some individuals harboring loss-of-function mutants in KCNQ1 or KCNE1 in both alleles succumb to Jervell and Lange-Nielsen Syndrome (JLNS), comprising both LQTS and sensorineural deafness." (PMID 24478792, 2014).
Romano-Ward syndrome (3 papers, 2014 to 2024). "Mutations in KCNQ1 and KCNE1 leads to malfunctioning of the channel and thus cause Romano-Ward syndrome and Jervell and Lange-Nielsen syndrome." (PMID 34722422, 2021).
Tinnitus (3 papers, 2016 to 2025). Tinnitus is an auditory perception that can be described as the experience of sound, in the ear or in the head, in the absence of external acoustic stimulation. "KCNE1 and SLC12A2 were associated with tinnitus based on significance in only one genetic marker per gene (rs915539 in KCNE1, p = 0.018; rs10089 in SLC12A2, p = 0.026)." (PMID 28533738, 2017).
Jervell and Lange-Nielsen syndrome type 2 (2 papers, 2021 to 2022). "Mutations in voltage-gated potassium channel KCNE1 cause Jervell and Lange-Nielsen syndrome type 2 (JLNS2), resulting in congenital deafness and vestibular dysfunction." (PMID 33514733, 2021).
Aortic dissection (1 paper, 2022). Aortic dissection refers to a tear in the intimal layer of the aorta causing a separation between the intima and the medial layers of the aorta. "AGFG1, MCEMP1, IRAK3, KCNE1, and CLEC4D in module M37 were highly connected and strongly linked with AD, suggesting that these genes may help understand the pathogenesis of aortic dissection." (PMID 35178459, 2022).
breast carcinoma (1 paper, 2021). "Many studies have shown that potassium channels, including KCNN4, KCNA1, Kv11.1, KCNK9, KCNE1, and GIRK1 are involved in the regulation of malignant breast cancer transformation." (PMID 34195184, 2021).
cardiac hypertrophy (1 paper, 2022). "Moreover, transcriptome unbiased analysis of post-MI cardiomyocytes with GRK5 overexpression showed altered levels of several genes previously indicated to be involved in cardiac hypertrophy, remodeling or HF such as Kcne1, Efna5, Psmd8 and several regulators of the extracellular matrix." (PMID 33560342, 2022).
chronic heart failure (1 paper, 2025). "Upregulation of Kcne1 leads to a prolonged QTc interval in patients with chronic heart failure." (PMID 40607964, 2025).
co-infection (1 paper, 2013). "The co-infection of HEK293T cells with miR-1 and the 3’UTRs of KCNE1/KCNB2 plasmids resulted in lower luciferase activity compared with infection with the plasmid alone." (PMID 24386485, 2013).
depression (1 paper, 2023). "Based on these findings, we speculate that KCNE1 may also be involved in the neurophysiological mechanisms of stress recovery by modulating neuronal activity, thus presenting a therapeutic effect on depression." (PMID 37649561, 2023).
Hyperglycemia (1 paper, 2018). An increased concentration of glucose in the blood. "Moreover, the expression levels of mir-1, that has been proved to suppress KCNQ1 and KCNE1 because up-regulated by hyperglycemia, was also evaluated." (PMID 29707106, 2018).
ischemia (1 paper, 2012). A hypoperfusion of the BLOOD through an organ or tissue caused by a PATHOLOGIC CONSTRICTION or obstruction of its BLOOD VESSELS, or an absence of BLOOD CIRCULATION. "In canine hearts infarcted for 5 days, chronic ischemia decreased IKs current density and downregulated the expression of KCNQ1 and KCNE1 mRNA." (PMID 22384037, 2012). "However, the effect of transient and chronic ischemia on the expression of KCNQ1 and KCNE1 proteins has not been determined." (PMID 22384037, 2012).
lung carcinoma (1 paper, 2024). "Furthermore, we found that low expression of KCNE1, NPC2, and SFTPD promotes lung cancer cell proliferation and invasion and M2 macrophage polarization." (PMID 38509982, 2024). "To additionally validate the accuracy of the bioinformatics analysis findings, we first examined KCNE1 in normal Epithelial cells BEAS-2B and malignant epithelial cells (lung cancer cell lines, H1299, A549, and HCC827), NPC2, and the mRNA and protein expression of SFTPD." (PMID 38509982, 2024).
sudden cardiac death (1 paper, 2017). "Among these genetic anomalies, only four variants, i.e., KCNQ1, KCNE1, SCN1A, and CACNA1C, were previously associated with SUDEP or other disorders associated with sudden cardiac death (SCD)." (PMID 29261713, 2017).
uterine cancer (1 paper, 2019). Primary or metastatic malignant neoplasm involving the uterine corpus and/or the cervix. "With regard to cancer, KCNE1-3 are expressed in uterine cancer cell lines, in which they influence proliferation and a 5-fold and 3-fold upregulation of KCNE3 and KCNE4 respectively has been reported in gliobastoma datasets." (PMID 31071485, 2019). "The apoptotic influence of KCNE1 in U87-MG cells is proposed to occur through canonical K+ efflux through Kv7.1, inducing decreased cytoplasmic K+, a known apoptotic trigger, whereas KCNE1 induces uterine cancer cell proliferation via modulation of HERG channels." (PMID 31071485, 2019).
ventricular fibrillation (1 paper, 2011). A disorder characterized by an electrocardiographic finding of a rapid grossly irregular ventricular rhythm with marked variability in QRS cycle length, morphology, and amplitude. "Two variants, i.e. p.D85N in KCNE1 and p.T8A in KCNE2 have previously been associated with increased risk for drug-induced ventricular fibrillation." (PMID 21967835, 2011).
viral infection (1 paper, 2013). "First, KCNE1 and KCNB2 could not be knocked down at the single-cell level to investigate the changes of IKs, and AERP in atrial cells because of the low cell viability after viral infection and the lack of the specific KCNE1 and KCNB2 inhibitors in rabbits." (PMID 24386485, 2013).
heart disease (5 papers, 2015 to 2026). "No pathogenic mutations of up to 50 other cardiac genes (including KCNE1) responsible for inherited heart diseases were identified." (PMID 25889101, 2015). "A Japanese study on 9 cases of SUDEP performed next-generation sequencing to examine 73 genes related to inherited heart disease: the Authors found KCNE1 as pathogenic variants (together with KCNE1) and also 3 other potentially pathogenic variants (MYH6, DSP, DSG2) according to in silico analysis." (PMID 41062843, 2026). "In addition, the human KCNQ1/KCNE1 channel, closely related to heart disease, was shortage of potent peptide blocker until now." (PMID 29925780, 2018).
cancer (3 papers, 2018 to 2024). A tumor composed of atypical neoplastic, often pleomorphic cells that invade other tissues. "KCNE1 was not expressed in cancer tissues but showed a significant expression in normal tissues." (PMID 37046674, 2023).
cardiovascular diseases (3 papers, 2015 to 2021). "In addition, several ion channels are modulated by STS and its precursor Tanshinone IIA in some cardiovascular disease models, such as human cardiac KCNQ1/KCNE1 (I-Ks) K+ channels, high conductance Ca2+ activated K+ channels (BKCa), KV2.1 and KV1.5." (PMID 28542554, 2017).
tumour (3 papers, 2023 to 2024). "The expression of the classical accessory subunit KCNE1, which is physiologically complexed with hERG1 in the heart and is substituted by the β1 integrin in tumours, was also evaluated, by analysing the KCNE1 transcripts." (PMID 37046674, 2023). "Following the overexpression of KCNE1, NPC2, and SFTPD, M0 macrophages exhibited a substantial reduction in the polarization of M2 macrophages as well as the quantity of tumor-promoting cytokines that were produced by the cells." (PMID 38509982, 2024). "Finally, we characterized the expression of three LSAGs (KCNE1, NPC2, and SFTPD) in malignant lung epithelium and assessed their impact on tumor malignancy related phenotypes." (PMID 38509982, 2024). "Therefore, to further culture H1299 cells with HCC827 and M0 macrophages, we found that after over-expression of KCNE1, NPC2, SFTPD, M0 macrophage polarization significantly decreased, and the amount of tumor-promoting cytokines secreted by cells was significantly reduced." (PMID 38509982, 2024).
infection (2 papers, 2013 to 2024). The state of being infected such as from the introduction of a foreign agent such as serum, vaccine, antigenic substance or organism. "However, AMO-1 infection reversed the A-TP-induced upregulation of miRNA-1 to approximately 49% of the pacing group, and recovered the expression levels of KCNE1 and KCNB2 (mRNA: to approximately 1.2-fold and 1.7-fold of the pacing group, respectively)." (PMID 24386485, 2013). "The expression levels of KCNE1 and KCNB2 were further downregulated (mRNA: to approximately 45% and 37% of the pacing group, respectively) by miR-1 overexpression via in vivo infection." (PMID 24386485, 2013).
KCNE1 also shares sentences with these, for which no sentence is quoted: cardiac arrhythmias (8 papers); Brugada syndrome (4); short QT syndrome (4); Congenital Long QT Syndromes (3); Diabetes (2); Hearing impairment (2); Menière's disease (2); Stroke (2); Ventricular arrhythmia (2); acquired long QT syndrome (1); acute myelogenous leukaemia (1); acute myocardial infarction (1); age-related hearing loss (1); Areflexia (1); astroglioma (1); atherosclerosis (1); cardiac arrest (1); catecholaminergic polymorphic ventricular tachycardia (1); catecholaminergic polymorphic ventricular tachycardia type 1 (1); cerebellar ataxia (1); cerebrovascular disease (1); Down syndrome (1); familial atrial fibrillation (1); lung adenocarcinoma (1); optic atrophy (1); otitis media (1); Pes cavus (1); polymorphic ventricular tachycardia (1); Sepsis (1); sick sinus syndrome (1).
A further 4 diseases each share a sentence with KCNE1 in 1 paper.